TRPV1 (transient receptor potential cation channel subfamily V member 1)
Diseases named in the same sentence as TRPV1 in open-access papers (continued):
Sharing a sentence is not in itself a finding about the gene and the disease.
Stroke (17 papers, 2011 to 2025). Sudden impairment of blood flow to a part of the brain due to occlusion or rupture of an artery to the brain. "Numerous recent investigations have intimated that TRPV1 is implicated in stroke pathophysiology, yet the particular mechanism eludes comprehension." (PMID 37718934, 2024). "OD in patients with post-stroke OD and acute stimulation with TRPV1 agonists caused a significant increase in SSF, further suggesting the potential role of pharmacological stimulation of sensory pathways as a therapeutic strategy for CPG activation in patients with OD." (PMID 33799960, 2021). "The TRPV1-mediated hypothermia also attenuates secondary neuronal loss and astrogliosis in the ipsilateral thalamus and reduces the thalamic fiber loss at one month post-stroke." (PMID 29247238, 2017). "The stroke induction led to a significant reduction in water consumption in both the TRPV1‐scramble and TRPV1‐knockdown groups." (PMID 37718934, 2024). "Several recent studies have indicated that TRPV1 participates in stroke pathophysiology, but the precise mechanism remains elusive." (PMID 36527242, 2023). "In addition to acute stroke management, long‐term TRPV1 activation may help reduce stroke risk." (PMID 36527242, 2023). "Our observation that TRPV1 channels were activated for the entire 10 min period in the ischemic stroke group indicates that these channels are also involved in post-stroke headache." (PMID 36293444, 2022). "The effect of sensory stimulation with capsaicin 10−5 M (TRPV1 agonist) was evaluated in 17 patients with post-stroke OD, using the SSF." (PMID 33799960, 2021). "We studied the effect of age and gender on spontaneous swallowing frequency (SSF) in healthy volunteers and assessed basal SSF and TRPV1 stimulation effect on SSF in patients with post-stroke oropharyngeal dysphagia (OD)." (PMID 33799960, 2021). "Recently, the TRPV1 antagonist AMG9810 was found to confer neuroprotection by attenuating TNFα production in a rodent model of stroke." (PMID 31223430, 2019). "We demonstrated significant functional recovery in DHC treated stroke mice, suggesting that neuroprotection by a single treatment of TRPV1-mediated hypothermia is robust and lasting." (PMID 29247238, 2017). "Rinvanil, a synthetic TRPV1 agonist, demonstrated an effect of hypothermia and permanent neuroprotection in stroke animal model." (PMID 29088731, 2017). "Ours and other studies have demonstrated that TRPV1-mediated pharmacological hypothermia decreases the cortical injury and provides neuroprotection after 24 hours cerebral reperfusion in the stroke model." (PMID 29247238, 2017). "TRPV1 modulates T cell activation and differentiation, which may indirectly affect γδ T cell activity and consequently influence post-stroke neuronal injury." (PMID 40746532, 2025). "TRPC1/3/4/6, TRPV1/2/4, and TRPM2/4/7 channels have been implicated in stroke pathophysiology." (PMID 36527242, 2023). "Thus, the potential effects of TRPV1 for stroke therapy remain controversial and warrant careful investigation." (PMID 36527242, 2023). "Interestingly, the involvement of TRPV1 channels in stroke pathophysiology was also shown in other studies." (PMID 36293444, 2022). "Interestingly, the gene expression of Trpv1 was increased post stroke, and Trpv1 inhibition exhibits some neuro-protective effects during brain ischemia in mice." (PMID 33806707, 2021). "Thus, in the present study, we investigated the effects of TRPV1-mediated hypothermia on functional recovery by a long-term serial assessment of behavioral function during post-stroke recovery." (PMID 29247238, 2017). "Therefore, the current study investigates the long-term effects of TRPV1-mediated pharmacological hypothermia on both primary and secondary post-stroke injury and functional outcome during one month after stroke." (PMID 29247238, 2017).
Stroke (continued). "In summary, our study demonstrates that TRPV1-mediated hypothermia initiated 3.5 hours after cerebral ischemia significantly reduced both cortical injury (primary injury site) and thalamic injury (remote secondary injury) assessed at one month post-stroke." (PMID 29247238, 2017). "Finally, a single eight-hour treatment of TRPV1-mediated hypothermia provides persistent behavioral recovery through one month post-stroke." (PMID 29247238, 2017). "However, despite its neuroprotective effects in the acute phase after stroke, it is unclear whether TRPV1-mediated hypothermia has long-term benefit on ischemic injury and functional recovery." (PMID 29247238, 2017). "The TRPC1/3/4/6, TRPV1/2/4, and TRPM2/4/7 channels have been extensively investigated focusing on their effects on neurons and gliocytes post‐stroke." (PMID 36527242, 2023). "In summary, we propose that in stroke-related conditions, mechanosensitive Piezo1 channels and nociceptive TRPV1 channels in meningeal afferents are sensitized and thus may contribute to the generation of post-stroke headaches." (PMID 36293444, 2022). "Pathological changes in brain temperature or pH, for example after a severe stroke, may influence TRPV1 activity, but normal brain pH and temperature are unlikely to result in TRPV1 activation per se." (PMID 21249195, 2011). "Similarly, the results showed that the EMG response was impaired by stroke induction and restored by EA, but the EMG response was not recovered by EA treatment in the TRPV1‐knockdown group (p < 0.05; p < 0.01)." (PMID 37718934, 2024).
dry eye (16 papers, 2015 to 2026). "Together, these results indicate that TRPV1 is indispensable for dry eye-induced cold allodynia, and pharmacological suppression of TRPV1 is a promising therapeutic strategy for dry eye-associated cold allodynia." (PMID 31831729, 2019). "TRPV1 activation may also cause dry eye discomfort through the excitation of LB-HT cold thermoreceptors that detect nociceptive ocular dryness." (PMID 33424555, 2020). "Furthermore, pharmacological blockade of TRPV1 using AMG9810 effectively alleviated dry eye-associated cold allodynia in WT mice." (PMID 31831729, 2019). "Moreover, this line circumvents dry eye-associated pathological changes and inflammation, which may introduce confounding factors in studying the involvement of TRPV1." (PMID 31831729, 2019). "Blockade of TRPV1 signaling by ocular topical administration was previously shown to decrease the severity of dry eye and other ocular surface inflammatory disorders in mice." (PMID 38630767, 2024). "Tear film hyperosmolarity induces dry eye syndrome (DES) through transient receptor potential vanilloid type 1 (TRPV1) activation." (PMID 37511574, 2023). "These responses are pertinent to the in vivo condition since TRPV1 activation is documented to be induced by such stresses and it is alleged to contribute to dry eye symptomology." (PMID 33637945, 2021). "It is likely that this imposed stress is pertinent to dry eye induced ocular pain even though in these patients the hyperosmotic threshold for inducing pain through TRPV1 activation is unclear." (PMID 33637945, 2021). "In conclusion, chronic tear deficiency sensitizes the TRPV1-mediated response in LB-HT cold-sensitive and cold-insensitive polymodal nerves in the cornea, which may serve as therapeutic targets of spontaneous dry eye discomfort and hyperalgesia to nociceptive stimuli in aqueous-deficient dry eyes." (PMID 33424555, 2020). "In the same way, it has been observed that capsazepine, a TRPV-1 antagonist, prevented dry eye sensitization of cool cells to capsaicin and reduced polymodal responsiveness to acidic stimulation in an allergic eye model." (PMID 33362474, 2020). "Under pathological dry eye conditions, the expression of TRPV1 is further upregulated in TRPM8+ neurons." (PMID 31831729, 2019). "Trpv1−/− mice with dry eye displayed significantly reduced eye closing responses to cryosim-3 and innocuous cold stimulus (19 °C), compared with WT controls." (PMID 31831729, 2019). "Based on this observation Sylentis is currently evaluating a topical treatment with small interfering oligonucleotide of RNA (SiRNA) targeted to block the human TRPV1, Tivanisran, in Phase 3 studies in dry eye patients." (PMID 30805711, 2019). "Taken together, TRPM8 agonists should be evaluated in various dry eye animal models to determine if they reduce dry eye symptomology and dampen TRPV1-induced inflammation and corneal opacification." (PMID 26605361, 2015). "However, TRPV1 is significantly upregulated in TRPM8+ cold-sensing neurons in dry eye mice, compared with sham-operated mice." (PMID 31831729, 2019). "We found that Trpv1−/− mice displayed normal basal tear secretion before the dry eye surgery." (PMID 31831729, 2019). "Notably, TRPV1 can be activated by hypertonicity similar to patients with dry eyes." (PMID 29238714, 2017). "It was also demonstrated that TRPV1 activation in corneal epithelial cells by hypertonic media, similar to those observed in tears of dry eye patients, induces increased pro-inflammatory and chemoattractant release, which may contribute to the development of inflammation in dry eye patients." (PMID 27563913, 2016). "Furthermore, hypertonic stresses identical to those described in some dry eye patient tears elicited through TRPV1 channel activation, raised proinflammatory cytokine levels by eliciting mitogen-activated protein kinase (MAPK) and nuclear factor-κB (NF-kB) activation." (PMID 26605361, 2015).
dry eye (continued). "While thyronamine activates TRPM8, TRPV1 stimulation by CAP is blocked, thereby protecting the dry eye." (PMID 29238714, 2017). "The activated TRPV1 induces proinflammatory cytokine (IL-6) release via MAPK signaling pathway and leads to inflammatory condition, allowing of dry eye." (PMID 29238714, 2017). "The goal of dry eye treatment is to somehow suppress both the elevated NGF levels and the dry eye symptomology in order to reduce the rises in inflammatory parameters (pro-inflammatory cytokine release), resulting from TRPV1 activation." (PMID 40422222, 2025). "We suggest that weak stimuli of TRPV1 below the nociceptive threshold under normal conditions activate LB-HT cold thermoreceptors and cold-insensitive polymodal nociceptors in DED and may result in dry eye discomfort and pain, respectively." (PMID 33424555, 2020). "Transient receptor potential cation channel vanilloid 1 (TRPV1) is a key receptor for sensory transduction in polymodal nociceptors and has shown to be activated by hyperosmolarity, corneal damage, inflammatory mediators etc., which are present in ocular surface diseases such as dry eye." (PMID 30805711, 2019). "Although our gene deletion and pharmacological blockade assays have shown that TRPV1 is necessary for dry eye-associated cold allodynia, it is unclear whether the upregulation of TRPV1 in TRPM8+ neurons alone (without dry eye) is sufficient for generating cold allodynia." (PMID 31831729, 2019). "After surgery, Trpv1−/− mice showed similar extents of reduced tear secretion and intensified corneal epithelial erosions as WT controls, indicating that TRPV1 is not involved in the pathogenesis of dry eye in this model." (PMID 31831729, 2019).
peripheral nerve injury (16 papers, 2008 to 2025). Injury to a peripheral nerve. "We showed that the increase in 5-mC at CpG sites in Cacna1b e37a locus following peripheral nerve injury, that induces long-lasting hyperalgesia, is associated with reduced Cacna1b e37a expression in Trpv1-lineage neurons." (PMID 32213287, 2020). "A similar gene expression pattern has been reported, mirroring the TRPV1 profile after a perineural capsaicin treatment, and such transcriptional reprogramming triggered by a peripheral nerve injury is well documented." (PMID 41515994, 2025). "In summary, Trpv1-Cre neurons mediate heat hyperalgesia following peripheral nerve injury through VGLUT2-mediated glutamatergic signaling." (PMID 25615623, 2015). "A body of evidence suggests that TRPV1 plays a role in chemotherapy-induced chronic peripheral neuropathy, similar to the neuropathic pain induced by peripheral nerve injury." (PMID 22839205, 2012). "Intrathecal injection of AVV9 shRNA TRPV1 could reduce hyperalgesia induced by a peripheral nerve injury model in mice." (PMID 34113239, 2021). "ATP may also potentiate TRPV1 activity, increase axonal transport and increase excitability via activation of P2Y2Rs which likely contributes to nociceptive signaling and hyperalgesia after peripheral nerve injury." (PMID 19108746, 2008). "To explore the potential mechanisms which baicalin involved in the prevention of neuropathic pain, we examined Trpv1 and Trpa1 mRNA expression in DRG of rats with peripheral nerve injury using quantitative RT‐PCR method." (PMID 32613759, 2020). "Moreover, baicalin administration, reversed mRNA expression level of TRPV1 and suppressed TRPV1 upregulation and phosphorylation of extracellular signal-regulated kinases (MAPK/ERK pathway) in DRG neurons after peripheral nerve injury might account for the anti-nociceptive mechanism of baicalin." (PMID 37151956, 2023).
type 1 diabetes (16 papers, 2008 to 2026). "Type 1 diabetes is an autoimmune disease and TRPV1 is potentially associated with autoimmune abnormalities." (PMID 39619328, 2024). "Future research on this topic will contribute to a greater understanding of diseases where vitamin D deficiency and TRPV1 activity have been associated, such as chronic pain, and autoimmune diseases including multiple sclerosis and type 1 diabetes." (PMID 33825665, 2021). "Several studies have implicated TRPV1 in the development of diabetic peripheral neuropathy in animal models of type 1 diabetes and in humans." (PMID 24861977, 2014). "In humans, the SNP rs222747 (M315I) variant of the TRPV1 gene is significantly increased in the type 1 diabetic patients in an Ashkenazi Jewish population, suggesting that TRPV1 may be a susceptible gene for type 1 diabetes in some ethnic groups." (PMID 32168890, 2020). "Several studies, using streptozotocin (STZ)-treated mice, a model of type 1 diabetes, reported that in DRG neurons, elevated TRPV1 expression is associated with hyperalgesia and decreased TRPV1 expression is linked to loss of pain sensation (hypoalgesia)." (PMID 30795543, 2019). "This suggests the clinical utility of TRPV1 antagonists or agonist-induced desensitization of TRPV1 to treat type 1 diabetes." (PMID 24861977, 2014). "This suggests that these neurons may induce type 1 diabetes by modulating T cell proliferation and activity through substance P release, TRPV1 as a potential therapeutic target for Type 1 diabetes." (PMID 41569118, 2026). "This study used an Ins2+/Akita mouse model and proposed that, in poorly controlled type 1 diabetes, the accelerated rate of TRPV1 desensitization in dorsal root ganglion neurons may decreases TRPV1 activity and contributes to peripheral diabetic neuropathy." (PMID 35011580, 2021). "Interestingly, preliminary data suggest TRPV1 as a target of vitamin D regulation in the pathogenesis of type 1 diabetes, with vitamin D acting as a TRPV1 inhibitor to reduce activation of naïve T cells." (PMID 34673019, 2021). "Taken together, these data suggest that TRPV1 may influence insulin secretion and type 1 diabetes acting via a number of different cell types within the pancreas." (PMID 30108548, 2018). "We hypothesized that microvascular abnormalities, especially impaired TRPV-1 mediated vasodilation, can be found in type 1 diabetes." (PMID 28287157, 2017). "Interestingly, capsaicin also protects mice from the development of type 1 diabetes via TRPV1 by a mechanism related to gut-mediated immune tolerance." (PMID 27367653, 2016). "Known initially for its role in thermosensation and nociception, TRPV1 has garnered increasing attention in the context of autoimmune diseases like Type 1 Diabetes (T1D)." (PMID 41463571, 2025). "Initially recognized for its role in thermosensation and nociception, TRPV1 has emerged as a key regulator of immune modulation, β-cell physiology, vascular integrity, and neuroimmune signaling—processes central to the pathogenesis and progression of Type 1 Diabetes (T1D)." (PMID 41463571, 2025). "Using both streptozotocin (STZ)-induced and transgene-mediated murine models of type 1 diabetes (T1D), we demonstrate that Transient Receptor Potential Vanilloid 1 (TRPV1) expression varies with the neuropathic phenotype." (PMID 18312687, 2008). "A recent report indicated that TRPV1-mediated responses were restricted to liver-related preautonomic PVN neurons, and that this effect was eliminated in a model of type 1 diabetes due to receptor internalization." (PMID 23386808, 2013). "The idea that TRPV1 is an initiating factor mediating type 1 diabetes is challenged by the finding that TRPV1 isoform expressed in the non-obese diabetic (NOD) mouse possesses two mutations which render the channel less active and thereby should be less able to regulate the inflammatory process." (PMID 24861977, 2014).
bladder cancer (15 papers, 2012 to 2025). "Capsaicin was shown to activate transient receptor potential vanilloid 1 (TRPV1) to prevent the nuclear translocation of proliferating cell nuclear antigen, and was found to inhibit cell growth in a bladder cancer cell line in which TRPV1 is highly expressed." (PMID 34512323, 2021). "In the event of bladder cancer-promoted neuronal TRPV1 expression one would also expect strengthening of TRPV1-dependent afferent limb of micturition reflex." (PMID 33184390, 2020). "In human cancer, TRPV1 has been found to activate a cell death program in prostate, colon, pancreas, breast and bladder cancer." (PMID 27829230, 2016). "We found that TRPV1 expressed in 786-O at both mRNA and protein levels, and two bladder cancer lines T24 and 5637 were taken as the positive controls of TRPV1 expression, which were verified in the previous studies of our research team." (PMID 27729033, 2016). "TRPV1-mediated inhibition of migration has been analyzed more in detail in a recent study in bladder cancer." (PMID 24204345, 2013). "Besides, such capsaicin-provoked TRPV1 activation had also resulted in imparting a positive symbiotic effect with an anti-cancer drug named pirarubicin (THP) for treating bladder cancer." (PMID 36234927, 2022). "However, three other studies propose an anti-migratory and anti-invasive role for TRPV1 in lung, cervical and bladder cancer cell." (PMID 24204345, 2013). "The knowledge of the mechanism controlling TRPV1 expression might improve the diagnosis and new therapeutic strategies in bladder cancer." (PMID 22523714, 2012). "Thus, it is rational and desirable the use of TRPV1 antagonists as adjuvant in combination to classic chemotherapy for bladder cancer treatment." (PMID 22523714, 2012). "Moreover, TRPV1 is differentially expressed in the bladder cancer cell lines 5637 and T24." (PMID 32545311, 2020). "Therefore, TRPV1 stimulation may represent a strategy to increase the efficacy of traditional chemotherapeutic agents against bladder cancer." (PMID 32545311, 2020). "In bladder cancer, the interaction of CPS with its receptor TRPV1 increases PD-L1 expression, promoting a tumorigenic effect and also providing a target for anti-PD-1/PD-L1 immunotherapy." (PMID 35681623, 2022). "In this regard, we have recently assessed the role of TRPV1 mRNA downregulation as a negative prognostic factor in patients with bladder cancer." (PMID 22523714, 2012). "Thus, in hepatocellular carcinoma, TRPV1 expression correlates with better prognosis of patients, while in bladder cancer its reduction represents a prognostic negative biomarker." (PMID 27829230, 2016). "In addition, recently findings indicated that capsaicin by triggering ROS production, mitochondrial membrane depolarization, also induced a TRPV1-dependent nonapoptotic cell death in T24 bladder cancer cells." (PMID 22523714, 2012).